ENTPD2 (ectonucleoside triphosphate diphosphohydrolase 2)
Description:
Catalyzes the hydrolysis of nucleoside triphosphates (NTPs) and diphosphates (NDPs), with a marked preference for triphosphonucleosides over diphosphonucleosides. The enzyme sequentially removes phosphate groups in two successive steps, converting NTPs to nucleoside monophosphates (NMPs) via NDP intermediates. This activity contributes to the regulation of extracellular nucleotides levels. ATP hydrolysis is characterized by fast ADP accumulation and delayed AMP formation, reflecting limited ADP hydrolase activity (By similarity). Hydrolyzes ADP and UDP only to a marginal extent, and does not hydrolyze AMP. All nucleoside 5'-diphosphates are hydrolyzed at rates lower than those of their corresponding triphosphates (By similarity). [Isoform gamma]: Catalytically inactive. [Isoform Short]: Catalytically inactive.
Synonyms: CD39L1; NTPDase-2
Tractability: Antibody: its Gene Ontology location is reachable by antibodies, with high confidence; UniProt places it where antibodies can reach, with medium confidence; UniProt predicts a signal peptide or a membrane-spanning region. PROTAC: its protein half-life has been measured; a small molecule that binds it is known.
Target class: Enzyme; Hydrolase
Gene: Protein-coding gene on chromosome 9 (137,048,107 to 137,054,061, reverse strand). Ensembl gene ENSG00000054179.
Subcellular location: Cell membrane (Isoform Long); Endoplasmic reticulum membrane (Isoform Short); Endoplasmic reticulum membrane (Isoform gamma)
Pathways (Reactome):
Metabolism: Phosphate bond hydrolysis by NTPDase proteins
Gene Ontology:
Molecular function: ADP phosphatase activity; apyrase activity; ATP hydrolysis activity; CDP phosphatase activity; CTPase activity; GDP phosphatase activity; GTPase activity; IDP phosphatase activity; ITPase activity; nucleoside diphosphate phosphatase activity; protein binding; ribonucleoside triphosphate phosphatase activity; UDP phosphatase activity; hydrolase activity; pyrophosphatase activity
Biological process: ribonucleoside triphosphate catabolic process; nucleoside diphosphate catabolic process
Cellular component: endoplasmic reticulum membrane; extracellular exosome; plasma membrane; basement membrane
Genetic constraint (gnomAD): Loss-of-function variants: 49 observed, 45.13 expected, observed/expected ratio (o/e) 1.09, 90% interval 0.86 to 1.38. The synonymous counts are far from expectation, so gnomAD's model fits this gene poorly and the ratio says little. Missense variants: 706 observed, 613.41 expected, observed/expected ratio (o/e) 1.15, 90% interval 1.08 to 1.23. Synonymous variants: 316 observed, 256.56 expected, observed/expected ratio (o/e) 1.23, 90% interval 1.12 to 1.35.
Homologues: Orthologues: chimpanzee ENTPD2 (99% identical), macaque ENTPD2 (91% identical), pig ENTPD2 (85% identical), guinea pig ENTPD2 (85% identical), mouse Entpd2 (83% identical), rat Entpd2 (82% identical), dog ENTPD2 (82% identical), tropical clawed frog entpd2 (57% identical), zebrafish entpd2a.1 (49% identical), zebrafish entpd2b (47% identical), zebrafish entpd2a.2 (46% identical). Paralogues in human: ENTPD8 (43% identical), ENTPD3 (41% identical), ENTPD1 (39% identical), ENTPD7 (28% identical), ENTPD4 (26% identical), ENTPD5 (23% identical), ENTPD6 (22% identical).
Diseases named in the same sentence as ENTPD2 in open-access papers:
ENTPD2 is named in the same sentence as 43 diseases in open-access papers, as found by Europe PMC text mining. Sharing a sentence is not in itself a finding about the gene and the disease. The quoted sentences say what the papers report.
hepatocellular carcinoma (18 papers, 2017 to 2024). A malignant tumor that arises from hepatocytes. "HIF‐1 induces extracellular nucleoside triphosphate diphosphate hydrolase 2 (ENTPD2/CD39L1) overexpression in hepatocellular carcinoma clinical specimens." (PMID 36703877, 2023). "ENTPD2 was found to be elevated in hepatocellular carcinoma, indicating an unfavorable prognosis for patients." (PMID 35557945, 2022). "Recent reports considered ENTPD2 relevant for the lung adenocarcinoma and hepatocellular carcinoma transcriptomic signatures." (PMID 34209090, 2021). "Another example published in Nature Communications describes the HIF-1-mediated expression of ectoenzyme, ectonucleoside triphosphate diphosphohydrolase 2 (ENTPD2), which promotes the maintenance of MDSCs in a murine hepatocellular carcinoma model." (PMID 32316260, 2020). "Here, the authors show that in hepatocellular carcinoma, hypoxia induces the expression of ENTPD2 on cancer cells leading to elevated extracellular 5′-AMP, which in turn promote the maintenance of MDSCs by preventing their differentiation." (PMID 28894087, 2017). "Additionally, ENTPD2 has been proven to impede the differentiation of myeloid-derived suppressor cells, which can induce immunosuppression in hepatocellular carcinoma." (PMID 35557945, 2022). "In human hepatocellular carcinoma (HCC), entonucleoside triphosphate diphosphohydrolase 2 (ENTPD2), a direct transcriptional target of HIF-1α, is predominantly upregulated in hypoxia." (PMID 37460927, 2023). "To date, only Chiu has reported a correlation between ENTPD2 expression and M-MDSC differentiation in hepatocellular carcinoma." (PMID 38755598, 2024). "Ectonucleoside triphosphate diphosphohydrolase 2 (ENTPD2), an ecto-ATPase key for MDSC function and accumulation, is highly expressed in hepatocellular carcinoma cell lines owing to tumor hypoxia." (PMID 31535086, 2019). "Using hepatocellular carcinoma (HCC) as a cancer model, we show that hypoxia, through stabilization of hypoxia-inducible factor-1 (HIF-1), induces ectoenzyme, ectonucleoside triphosphate diphosphohydrolase 2 (ENTPD2/CD39L1), in cancer cells, causing its overexpression in HCC clinical specimens." (PMID 28894087, 2017). "have revealed that in MDSCs derived from hepatocellular carcinoma patients, hypoxia activates HIF-1, leading to the upregulation of ectonucleoside triphosphate diphosphohydrolase 2 (ENTPD2) expression, which subsequently facilitates the enzymatic hydrolysis of extracellular ATP into 5’-AMP." (PMID 39575238, 2024). "In hepatocellular carcinoma, these myeloid-derived cells can be accumulated in the hypoxic TME through C–C motif chemokine ligand 26 (CCL26) or through ectonucleoside triphosphate diphosphohydrolase 2 (ENTPD2)." (PMID 36260158, 2023). "In the hepatocellular carcinoma model, hypoxia promotes stabilization of HIF1α which induces increased expression of ectoenzyme, ectonucleoside triphosphate diphosphohydrolase 2 (ENTPD2/CD39L1) in cancer cells." (PMID 35122833, 2022).
lung adenocarcinoma (5 papers, 2021 to 2024). A carcinoma that arises from the lung and is characterized by the presence of malignant glandular epithelial cells. "Studies report using the expression levels of ENTPD2 for survival prognostication in gastric cancer, lung adenocarcinoma, and COVID-19." (PMID 39595122, 2024). "Inhibition of ENTPD2 suppresses the formation and migration of lung adenocarcinoma cells." (PMID 36353226, 2022). "We used ENTPD2 inhibitor POM-1 in 5 lung cancer cell lines, found that it could inhibit the formation of colonies in A549 and PC9, decreased colony-forming was also observed in H1975, which were all lung adenocarcinoma cell lines." (PMID 33858449, 2021).
glioma (4 papers, 2021 to 2023). A benign or malignant brain and spinal cord tumor that arises from glial cells (astrocytes, oligodendrocytes, ependymal cells). "ENTPD2 upregulation is demonstrated in papillary thyroid carcinoma‐derived cells, esophageal cancer cells, gliomas cells, and liver cancer cells in contrast to normal cells." (PMID 33314730, 2021). "The upregulation of ENTPD2 is present in papillary thyroid carcinoma-derived cells, esophageal cancer cells, glioma cells, and liver cancer cells in comparison to normal cells." (PMID 37999212, 2023).
liver cancer (4 papers, 2020 to 2024). An epithelial or non-epithelial malignant neoplasm that arises from the liver. "The hypoxic microenvironment stimulates ENTPD2 overexpression mediated by hypoxia‐inducible factor‐1 (HIF‐1) in liver cancer cells." (PMID 33314730, 2021). "Overexpression of ENTPD2 can be regarded as a poor prognostic indicator of liver cancer." (PMID 33024640, 2020).
colitis (3 papers, 2019 to 2024). Inflammation of the colon. "Both Entpd2−/− and Entpd3−/− mice are more susceptible to DSS-induced colitis and Entpd2−/− colonic macrophages display a more pro-inflammatory phenotype as compared to wild type controls." (PMID 30941139, 2019). "Two groups analysed the functions of ENTPD2 in mice with dextran sulphate sodium-induced colitis, and showed that it plays an important role in barrier function, gut motility, and neuromuscular communication." (PMID 39595122, 2024). "In support, similar effects on barrier function and susceptibility to DSS-induced colitis are observed in animals lacking Entpd2 (NTPDase2), which is primarily expressed by enteric glia." (PMID 35166239, 2022).
COVID-19 (3 papers, 2022 to 2024). A disease caused by infection with severe acute respiratory syndrome coronavirus 2. "Particularly, this study reports upregulated ADA, BTC, DPP6, EDIL3, LIF, ENTPD2, Flt3L, and LRP1 in severe COVID-19 patients for the first time." (PMID 36428847, 2022). "In COVID-19 patients, reduced levels of ENTPD2 and PTN were observed in nonsurvivors of ICU stay, even after adjustment." (PMID 35967328, 2022). "Furthermore, this study reports markers including ADA, BTC, DPP6, EDIL3, LIF, ENTPD2, Flt3L, and LRP1 to be upregulated in severe COVID-19 patients; hence, they are proposed as novel biomarkers for severe cases of COVID-19." (PMID 36428847, 2022).
Alzheimer disease (2 papers, 2024 to 2025). A progressive, neurodegenerative disease characterized by loss of function and death of nerve cells in several areas of the brain leading to loss of cognitive function such as memory and language. "An increase in ENTPD2 levels was reported in the entorhinal cortex and precuneus postmortem tissue of subjects with Alzheimer’s disease at later stages of the disorder (stages III-IV and V-VI) compared with controls." (PMID 39404420, 2024).
gastric cancer (2 papers, 2023 to 2024). A primary or metastatic malignant neoplasm involving the stomach. "In this study, the gastric cancer patients with high expression of CTLA4 and ENTPD2 had a better survival prognosis, with high expression of CLDN6, EMB, GPR15, VWF and AKR1B1 suggesting poor prognosis, which was consistent with previous studies." (PMID 37066015, 2023).
liver fibrosis (2 papers, 2020). "Furthermore, active Entpd2 protects versus chemical-induced liver fibrosis; in another study, Entpd2 deletion was without effects in liver-induced fibrosis." (PMID 32331389, 2020).
lung carcinoma (2 papers, 2020 to 2021). "Meanwhile, we firstly developed the function of ENTPD2 on cells colon formation and migration in 5 lung cancer cell lines." (PMID 33858449, 2021). "Finally, we confirmed six MRGs protein and mRNA expression in six lung cancer cell lines and firstly found that ENTPD2 might played an important role on LUAD cells colon formation and migration." (PMID 33858449, 2021). "The protein expression levels of ALDOA, ENTPD2, LDHA, TYMS and CAT were investigated in 5 lung cancer cell lines (A549, H460, H1299, H1975, PC9), normal airway epithelial cells (16HBE) as control." (PMID 33858449, 2021). "The same with the results we have developed from bioinformatics, ALDOA, ENTPD2, LDHA, TYMS were significantly increased in 5 lung cancer cell line, comparing with in 16HBE." (PMID 33858449, 2021). "The mRNA expression levels of CAT, ENTPD2 and LDHA were also investigated in 6 lung cancer cell lines (A549, H460, H1299, H1975, PC9, Lewis), 16HBE as control." (PMID 33858449, 2021). "The mechanism and function of ENTPD2 in lung cancer were not reported previously." (PMID 33193873, 2020).
acute liver failure (1 paper, 2020). Rapid deterioration of liver function causing encephalopathy and coagulopathy. "Real-time qPCR of whole liver tissue after induction of acute liver failure by APAP injection revealed that WT mice showed significant increases in Entpd2 expression at six hours when compared to animals treated with vehicle control." (PMID 32825435, 2020).
breast carcinoma (1 paper, 2017). "Eight loci (PABPC4L, APBA2, FAM189A1, FUT7, ENTPD2, NPDC1, C9orf139 and L1CAM) were associated with risks for both breast cancer and ovarian cancer (P<0.05)." (PMID 28145423, 2017).
colon adenocarcinoma (1 paper, 2024). "Analysis via the TIMER2 resource revealed significant ENTPD2 overexpression in tissues of multiple human tumors, including colon adenocarcinoma (COAD), compared to the paired normal tissues." (PMID 38755598, 2024).
colon cancer (1 paper, 2024). "In patients with colon cancer, the serum level of exosomal ENTPD2 is positively associated with advanced TNM stage and high tumor invasion depth." (PMID 38755598, 2024). "Colon cancer cell-derived exosomes transfer ENTPD2 as an extracellular ATP scavenger, thus impairing CD8+ T-cell function by inhibiting P2 X7R-mediated NFATc1 activation and promoting the activity of the adenosine-A2AR pathway." (PMID 38755598, 2024). "Our study suggests that exosomal ENTPD2, originated from colon cancer cells, contributes to the immunosuppressive microenvironment by promoting ATP–adenosine metabolism." (PMID 38755598, 2024). "We analyzed the expression levels of ENTPD2 in serum exosomes from 59 colon cancer patients and 28 healthy donors." (PMID 38755598, 2024). "Herein, we prepared conditioned medium (CM), CM-Exosome, and Exosome from colon cancer cells to investigate differences in ATP hydrolysis, which is regulated primarily by ENTPD2." (PMID 38755598, 2024). "Our findings showed that ENTPD2 was released via exosomes from colon cancer cells to suppress CD8+ T-cell function by both limiting ATP-P2 X7 receptor (P2 X7R)-mediated NFATc1 nuclear transcription and promoting the activity of the adenosine-A2AR pathway." (PMID 38755598, 2024). "Double-labelling immunofluorescence and western blotting were used to examine the expression of ENTPD2 in serum exosomes and colon cancer tissues." (PMID 38755598, 2024). "Together, these data suggest that high ENTPD2 expression in colon cancer cells has an inhibitory effect on the functional activity of CD8+ T cells in the TME." (PMID 38755598, 2024). "In patients with colon cancer, the serum level of exosomal ENTPD2 is increased and positively correlated with advanced TNM stage and high tumor invasion depth." (PMID 38755598, 2024). "An ATP hydrolysis assay, high-performance liquid chromatography (HPLC), and CCK8 and colony formation assays were used to determine the effects of ENTPD2 on the biological functions of colon cancer cells." (PMID 38755598, 2024). "Our research demonstrated for the first time that exosomes derived from colon cancer cells carry ENTPD2, which promotes ATP–adenosine metabolism and induces the formation of an immunosuppressive microenvironment." (PMID 38755598, 2024). "Herein, we demonstrated that colon cancer-derived exosomes harbour ENTPD2, which can effectively inhibit CD8+ T-cell function." (PMID 38755598, 2024). "We further discovered that ENTPD2 not only is expressed on the surface of colon cancer cell membranes but also is abundantly released into the extracellular space via exosomes." (PMID 38755598, 2024). "Subsequently, we evaluated exosomes derived from ENTPD2-knockdown colon cancer cells (ExoRKO−shENTPD2 and ExoDLD1−shENTPD2) and control colon cancer cells (ExoRKO−shNC and ExoDLD1−shNC), with the corresponding cell lysates used as controls." (PMID 38755598, 2024). "Collectively, both the in vitro and in vivo experimental results indicate that exosomal ENTPD2 derived from colon cancer cells can significantly inhibit the function of CD8+ T cells." (PMID 38755598, 2024). "We further found a significant positive correlation between the level of serum exosomal ENTPD2 and the level of ENTPD2 in paired colon cancer tissues." (PMID 38755598, 2024). "To elucidate the feasibility of ENTPD2 detection in the serum of patients with colon cancer, we isolated and characterized exosomes from the serum of patients with colon cancer." (PMID 38755598, 2024). "ENTPD2 is a principal ATP hydrolytic enzyme within colon cancer cells, and it primarily localizes within the cell membrane, with its catalytic site oriented towards the extracellular space." (PMID 38755598, 2024). "We therefore evaluated the potential physiological role of ENTPD2 in colon cancer cells." (PMID 38755598, 2024).